PTH (parathyroid hormone)
Diseases named in the same sentence as PTH in open-access papers (continued):
Sharing a sentence is not in itself a finding about the gene and the disease.
Hypercalcemia (continued). "Consequently, the analysis was redirected for independent PTH hypercalcemia, ruling out 25-hydroxycholecalciferol toxicity (24 ng/dl) (she actually had this deficiency)." (PMID 35664896, 2022). "Hypercalcemia with an elevated PTH level establishes the diagnosis." (PMID 36408083, 2022). "Investigation revealed hypercalcaemia; corrected calcium of 2.6 mmol/L (reference range: 2.21–2.52 mmol/L); PTH of 53.7ng/L (reference range: 15–65 ng/L) and an elevated 24-hour urine calcium of 10 mmol/24 (2.50–7.50 mmol/24hr) with positive genetic analysis and is managed conservatively." (PMID 36536367, 2022). "PHPT is characterized by hypercalcemia as well as inappropriately elevated PTH, both of which may alter the functional status of the HPA axis." (PMID 35974370, 2022). "More over the biology shows a severe hypercalcemia with a markedly elevated PTH level." (PMID 36578799, 2022). "However, the Kidney Disease Outcomes Quality Initiative (KDOQI) guideline recommends that parathyroidectomy should be considered when the PTH level reaches 800 pg/mL, or when the patient suffers from medically intractable hypercalcemia and hyperphosphatemia." (PMID 36295623, 2022). "In addition to elevated serum 25(OH)D3 concentrations, vitamin D toxicity can be diagnosed by severe hypercalcemia and by very low or undetectable PTH activity." (PMID 36235615, 2022). "Abnormally elevated parathyroid hormone (PTH) and hypercalcemia might cause a series of clinical symptoms, such as osteoporosis, fracture, nephrolithiasis, reduced renal function, impaired neurocognitive features, and even hypercalcemic crisis." (PMID 35381852, 2022). "Similarly to PHPT, familial hypocalciuric hypercalcemia (FHH) is a state that also leads to hypercalcemia and the elevation of PTH." (PMID 36142318, 2022). "It is characterized by severe hypercalcemia and low or undetectable PTH hormone levels." (PMID 34322336, 2021). "However, hypercalcemia promotes a reduction in PTH secretion and decreases vitamin D synthesis and calcium mobilization." (PMID 34113519, 2021). "The clinical manifestation may be life-threatening severe hypercalcemia (>3.5 mmol/L) with high serum PTH level, respiratory distress, hypotonia and severe hyperparathyroid bone disease with spontaneous bone fractures could develop in the affected neonates." (PMID 33528764, 2021). "Increased levels of PTH lead to hypercalcemia through increased renal tubular calcium reabsorption, stimulation of osteoclast-mediated bone resorption and increased renal synthesis of 1.25 (OH)2D3, which in turn promotes enhanced intestinal calcium and phosphate absorption." (PMID 33918966, 2021). "In addition, two patients (one each in the control and in the cachexia group) had inappropriately high PTH serum levels despite hypercalcemia, suggesting mild hyperparathyroidism." (PMID 34182958, 2021). "Parathyroidectomy may need to be considered if patients become unresponsive to SHPT treatment, have persistently elevated PTH levels, and refractory hypercalcaemia or hyperphosphataemia." (PMID 34170509, 2021). "On the contrary, PTH secretion is inhibited by hypercalcemia." (PMID 34959915, 2021). "Given the increasingly lower cost of genetic testing and the cost of follow up and unnecessary surgery, it may prudent to include genetic testing for FHH early on in patients with mild PTH-dependent hypercalcemia." (PMID 33499837, 2021). "This brings the situation of Hypervitaminosis D, which is presented with such health implications as abdominal pain, cardiac arrhythmias, hypercalcemia, and hypovolemia from renal sodium and water losses, neuropsychiatric disturbances, as well as suppressed parathyroid hormone level." (PMID 34557342, 2021). "More specific markers of PC are required for preoperative differential diagnosis since PA could be accompanied by severe course of PHPT with severe hypercalcemia and a significant increase in PTH, and vice versa, PC with a mild course and even normocalcaemia." (PMID 34505413, 2021).
Hypercalcemia (continued). "Patients may present with hypercalciuria and alternate between chronic phases with normal serum calcium but inappropriately high 1,25-(OH)2D and appropriately low PTH, and acute phases with hypercalcemia with suppressed PTH." (PMID 34721296, 2021). "Moreover, endogenous PTH has a catabolic function in bone, while the incidence of hypercalcemia and increased 1,25(OH)2D3 is lower in treatment with ABL when compared to teriparatide." (PMID 34760881, 2021). "It is generally characterized by hypercalcemia and elevated parathyroid hormone (PTH) levels." (PMID 33651201, 2021). "All patients had significant hypercalcemia and elevated PTH levels." (PMID 33993327, 2021). "It is estimated that 9–23 % of patients with PTH-dependent hypercalcemia who underwent failed neck exploration may have FHH." (PMID 33499837, 2021). "Infantile hypercalcemia (IH) is a rare genetic cause of nephrocalcinosis typically occurring in paediatric subjects and characterized by inappropriate increment of calcitriol with persistent hypercalcemia, absorptive hypercalciuria, suppressed parathyroid hormone level and nephrocalcinosis." (PMID 33952337, 2021). "Blood tests showed hypercalcemia (14.4 mg/dl, range 8.4–10) and low PTH (4.7 pg/ml, range 15–65)." (PMID 34093441, 2021). "Thus, it promotes PTH suppression with a lower incidence ofside effects, such as hyperphosphatemia and/or hypercalcemia." (PMID 34910799, 2021). "A more severe degree of trabecular bone demineralization and lower values of both spine and femur bone mineral density (BMD) were reported in MEN1 PHPT compared to sPHPT patients, despite a significantly younger age, lower serum levels of PTH, and usually a milder hypercalcemia." (PMID 34440663, 2021). "Hypercalcemia is reportedly present in approximately 5–10 % of patients with acromegaly and is usually parathyroid hormone (PTH)-dependent as a result of a coexisting parathyroid hyperplasia or adenoma, which are common in individuals with multiple endocrine adenomatosis-1 (MEN-1)." (PMID 33933067, 2021). "Primary hyperparathyroidism leads to hypercalcemia via overproduction of parathyroid hormone (PTH)." (PMID 34692360, 2021). "Only two cases with hetero-isodisomy also present hypercalcemia associated with low PTH, suggestive of IH phenotype; without confirmation of the involvement of the CYP24A1 gene." (PMID 33952337, 2021). "Primary hyperparathyroidism (pHPT) is an endocrine disorder caused by the excessive secretion of parathyroid hormone (PTH) by the parathyroid glands, with the diagnosis generally being established on the association of hypercalcemia, elevated PTH levels and high urinary calcium excretion." (PMID 34768698, 2021). "The therapeutic approach to this non-PTH dependent hypercalcemia is universal." (PMID 34258083, 2021). "Rarely, PTH levels are normal with concomitant hypercalcemia." (PMID 33839893, 2021). "Furthermore, the elevated levels of PTH, Ca2+, and Pi exceeded their original reference ranges and the proportions of subjects with hyperparathyroidemia, hypercalcemia and hyperphosphatemia increased after IS." (PMID 34899374, 2021). "The hypercalcemia started 10 months after surgery and her PTH levels were in the normal range." (PMID 33909856, 2021). "However, in the subgroup of patients with severe hypercalcemia, there was a relationship between the concentration of PTH, ionized calcium and the presence of anemia." (PMID 34766485, 2021). "As expected, PTH is reduced in the presence of hypercalcemia due to physiologic suppression." (PMID 33732556, 2021). "On the other hand, increased mitotic activity induced by hypercalcemia and elevated concentrations of angiogenic growth factors and fibroblast growth factor induced by PTH could stimulate tumor growth." (PMID 34158812, 2021). "With regard to PTH, it has been demonstrated to cross the blood brain barrier and be associated with depressed states independent of hypercalcemia or calciferol." (PMID 34722014, 2021).
Hypercalcemia (continued). "However, a systemic review and meta-analysis indicated that vitamin D supplement was efficient for restoring 25(OH)D levels with a decrease in serum PTH level and low incidence of hypercalcemia and hyperphosphatemia among patients on CKD and dialysis." (PMID 33791128, 2021). "Phosphate depletion increases calcitriol synthesis and may lead to hypercalcemia which supresses PTH levels." (PMID 31674171, 2020). "Hypercalcemia without elevated parathyroid hormone (PTH) level is most frequently due to an underlying neoplasm." (PMID 33008295, 2020). "The way that many studies identify NPHPT patients is by testing calcium and PTH at baseline, and retesting after some time to check whether they progressed to hypercalcemia." (PMID 32072184, 2020). "Therefore, the promotion of renal reabsorption of calcium by PTH and increased osteoclast and intestinal calcium absorption by 1,25(OH)2D lead to the occurrence of hypercalcemia." (PMID 33015068, 2020). "Vitamin D supplementation reduces serum PTH, without causing hypercalcemia and hypercalciuria, thus reducing the risk of nephrolithiasis." (PMID 32751307, 2020). "However, the greater correlation between PTH and serum calcium compared with 1,25(OH)D and serum calcium confirms PTH as the primary contributor to hypercalcemia." (PMID 33210066, 2020). "Blood tests disclosed hypercalcemia with increased intact PTH level." (PMID 32832168, 2020). "Whether cinacalcet would have a place in the immediate medical treatment of severe PTH-dependent hypercalcemia would warrant further study." (PMID 32621588, 2020). "On labs, he had hypercalcemia and suppressed parathyroid hormone (PTH) intact." (PMID 32206474, 2020). "As serum 1.25(OH)2D is high and FGF23 and PTH are reduced in such cases, secondary hypercalcemia and medullary calcinosis together with urolithiasis may be expected." (PMID 31514490, 2020). "Although PTH-induced endothelial dysfunction can lead to PRES in PHPT, the same does not hold true in PTH-independent causes of hypercalcemia as PTH levels are suppressed." (PMID 32129057, 2020). "Hypercalcemia may develop in patients with osteoporosis and treated with recombinant PTH (1‐84), and serum calcium correlates with urinary calcium excretion, serum ALP, and β‐CTX in these patients." (PMID 33145966, 2020). "Follow-up evaluation showed non-parathyroid hormone-mediated hypercalcemia." (PMID 32923244, 2020). "In the case of hypercalcemia, the response of aldosterone to Ang II is weakened, which may explain why PTH inhibits the secretion of aldosterone levels." (PMID 32973674, 2020). "Abnormalities in mineral metabolism in CKD include the development hyperphosphataemia, elevations in the phosphatonins fibroblast growth factor (FGF)-23 and parathyroid hormone (PTH), reduced circulating active 1,25-dihydroxyvitamin D and hypo- or hypercalcaemia." (PMID 32634148, 2020). "For example, a 10% increase in serum levels of parathyroid hormone above normal levels is sufficient to induce hyperparathyroidism; likewise, an increase of blood calcium from 100 to 104 mg (5% increase) is sufficient to create pathological hypercalcemia." (PMID 33231171, 2020). "High clinical suspicion is required for parathyroid carcinoma diagnosis in the presence of very high level of parathyroid hormone, marked hypercalcemia, and the existence of any thyroid nodule should be approached and the coexistence of other carcinomas should be considered." (PMID 32292610, 2020). "Familial hypocalciuric hypercalcemia (FHH) is a group of autosomal dominant genetic diseases, which is characterized by persistent hypercalcemia, hypophosphatemia, hypermagnesemia, normal or mildly elevated serum parathyroid hormone (PTH) levels and low urinary calcium excretion." (PMID 32871939, 2020). "If by any means possible, a diagnosis of hypercalcaemia should be followed by measurement of PTH levels, as this may help determine the necessity of immediate subsequent examinations/treatments." (PMID 32396134, 2020).
Hypercalcemia (continued). "Recipients with enlarged parathyroid gland may resist to cinacalcet-induced decrease in serum PTH, although the concomitant hypercalcemia may be corrected." (PMID 32913586, 2020). "PHPT patients usually present with hypercalcemia, hypophosphatemia, high PTH, and hyper ALP." (PMID 32871939, 2020). "Thus, a PTH replacement therapy that fully controls the disease, including episodes of hypercalcemia and hypocalcemia as well as hypercalciuria, remains an unmet need." (PMID 32212275, 2020). "Similarly, the albumin‐adjusted sCa showed a dose‐dependent, sustained response that correlated with the Free PTH profile, with control of FECa despite mild hypercalcemia in the higher dose cohorts." (PMID 32212275, 2020). "Finally, concurrent vitamin D deficiency did appear to exist in some subjects with PHP (group 2), leading to a lesser degree of hypercalcemia and 1,25(OH)D elevation despite a greater PTH concentration in comparison with group 1." (PMID 33210066, 2020). "Denosumab could be a treatment of first choice for PTH-related hypercalcemia, especially in severe renal impairment or when bisphosphonates are ineffective." (PMID 33112830, 2020). "The decreased number and expression of CaSR in hypertrophied parathyroid glands may be related to the proliferation of parathyroid tissue, resulting in inadequate suppression of PTH by calcium and high PTH even in the setting of hypercalcemia." (PMID 32961953, 2020). "Suppressed serum PTH levels may indicate a state of disequilibrium hypercalcemia due to for example, malignancies or vitamin D intoxication, which may worsen rapidly and necessitate immediate treatment." (PMID 32396134, 2020). "Medical therapy with cinacalcet demonstrated to be effective to control PTH over-secretion, and subsequent hypercalcemia, in patients who manifest PHPT recurrence or persistence despite one or more reoperations and in patients who are not suitable for parathyroidectomy." (PMID 32326947, 2020). "When multivariate analysis was performed using serum levels of hemoglobin, phosphorus, β‐CTX, tPINP, OC, 25‐(OH)2D3, PTH, creatinine, and uric acid, laboratory parameters (PTH, creatinine, uric acid, and hemoglobin) were found to be the most important factors of hypercalcemia." (PMID 33145966, 2020). "However, the observations that ABL and PTH leads to similar serum calcium concentrations in rodents is at variance with the clinical finding that treatment with ABL leads to a lower incidence of hypercalcemia than treatment with PTH." (PMID 33162940, 2020). "Local administration in the extraction socket in the study could reduce the systematic effects of PTH, such as hypercalcemia, which was reflected by the unaltered serum calcium level." (PMID 32348445, 2020). "Forty percent of patients with hypercalcemia had normal or mildly elevated PTH levels." (PMID 33145966, 2020). "The large heterogeneity of the study population with different types of PTH-related hypercalcemia (carcinoma and adenoma of parathyroid glands), different treatment schedules for the isotonic saline infusion and cinacalcet does not allow to fully estimate the impact of denosumab on serum calcium." (PMID 33112830, 2020). "Hypercalcemia suppresses PTH secretion and stimulates CaSR activity to enhance renal Ca excretion." (PMID 31241466, 2019). "Consequently, unexplained low-PTH hypercalcemia should lead physicians to suspect a Pneumocystis infection in KTR, even in the absence of infectious/respiratory symptoms." (PMID 31467367, 2019). "In dialysis patients, normal homeostasis of both calcium and phosphorus is compromised, resulting to hypercalcemia, hyperphosphatemia, elevated calcium phosphate products, high parathyroid hormone (PTH), and worsen secondary parathyroidism (SHPT) through a direct and indirect mechanism." (PMID 31281748, 2019). "PTH secretion is stimulated by hypocalcemia and suppressed by hypercalcemia." (PMID 31241466, 2019).
Hypercalcemia (continued). "At diagnosis mean serum calcium was 11.6 (SD 0.08; range 10.8–12.7) mg/dL, and was associated with decreased rates of PTH and upper normal levels of 1,25 dihydroxyvitamin D. We here report a comparable prevalence of PJP-associated hypercalcemia in our cohort of KTR (37%)." (PMID 31467367, 2019). "Single case reports have provided some evidence that anti-PTH immunotherapy may help prolonged control of hypercalcaemia unresponsive to conventional treatments, and control tumor growth, in some case achieving reduction of metastatic tumor burden." (PMID 31142320, 2019). "PC should be suspected in patients with severe PTH-dependent hypercalcemia or its complications, but may be overlooked because it is so rare." (PMID 31176307, 2019). "PHPT has a high prevalence in Western communities, yet evidence is sparse concerning the natural history and whether morbidity and long-term outcomes are related to hypercalcemia or plasma PTH concentrations or both." (PMID 31176307, 2019). "Rebound hypercalcemia may be related to elevated PTH and PTH receptors in people with recently closed growth plates or certain pathologies." (PMID 31687646, 2019). "In accordance with the guidelines for management of primary hyperparathyroidism by the American Association of Endocrine Surgeons, the diagnosis of parathyroid carcinoma should be considered in cases of primary hyperparathyroidism with marked elevation of PTH levels and severe hypercalcemia." (PMID 31708875, 2019). "The combination of hypercalcemia with suppressed PTH is suspicious of malignancy." (PMID 31687644, 2019). "Laboratory examination revealed markedly high PTH and absence of hypercalcemia along with vitamin D deficiency." (PMID 30820485, 2019). "Lithium affects PTH secretion and thereby causes PTH-dependent hypercalcemia, whereas the use of drugs such as thiazides (not uncommon in the elderly) and vitamin D can cause PTH-independent hypercalcemia." (PMID 29260296, 2018). "Frank vitamin-D toxicity might occur at even higher levels and is characterized biochemically by hypercalcemia, hyperphosphatermia, suppressed serum PTH concentrations, and markedly elevated 25(OH)D levels." (PMID 29955644, 2018). "Conversely, it can be assumed that hypercalcemia with low parathyroid hormone and high 1,25-dihydroxyvitamin D may reveal malakoplakia." (PMID 30290590, 2018). "During the study period, severe SHPT was observed in 18.3% of cases: Twenty-four patients were administrated cinacalcet for persistent serum PTH above 800 pg/mL (n = 18), serum PTH > 400 pg/mL with persistent hypercalcaemia (n = 2), or high serum bone marker level (n = 2)." (PMID 29912988, 2018). "In the setting of hypercalcemia, PTH level assessment is a must." (PMID 30157930, 2018). "The hypercalcemia suppresses PTH release and thus abrogates the stimulatory effect of PTH on FGF23." (PMID 29483574, 2018). "Hyperthyroidism is associated with mild hypercalcaemia, and even though a preserved PTH level was not expected, one patient with hyperthyroidism was excluded due to this reason." (PMID 29532143, 2018). "However, diagnosis is sometimes made after routine biochemical screening has revealed hypercalcemia in an asymptomatic individual who is then found to have raised PTH." (PMID 30157930, 2018). "Regular monitoring, involving TCa, PTH and vitamin D, would potentially identify all patients with tendencies towards hypercalcemia, whereby appropriate action could be taken." (PMID 29260296, 2018). "Complete blood cells count, levels of serum calcium and phosphorous, 25-hydroxyvitamin D, alkaline phosphatase (ALP), creatinine, thyroid-stimulating hormone (TSH), PTH have to be determined, and protein electrophoresis has to be performed to analyze bone turnover and identify hypercalcemia." (PMID 29890702, 2018).